DLC1 (DLC1 Rho GTPase activating protein)
Diseases named in the same sentence as DLC1 in open-access papers (continued):
Sharing a sentence is not in itself a finding about the gene and the disease.
tumor (158 papers, 2007 to 2026). "Here, we explored how the loss of the tumor suppressor DLC1 modulates EMT and MET processes in the TGFβ-responsive MCF10A model system." (PMID 40354489, 2025). "RNA sequencing indicates that NSUN5P2, Linc01694, and DLC1 in differential genes are associated with the cell cycle and the enhancement or inhibition of tumor cell proliferation and invasion, respectively." (PMID 40708858, 2025). "Seven cancer‐associated mutations in DLC1‐START were found to decrease tumor suppressive activity, highlighting the relevance of these actions for carcinogenesis." (PMID 38967113, 2024). "A protein whose RhoGAP activities and scaffolding contribute to tumor suppressor roles are encoded by the DLC1 gene, which is controlled in many forms of cancer by both genetic and nongenetic pathways." (PMID 38967113, 2024). "A previous investigation has demonstrated some RhoGAPs (e.g., DLC1) have a tumor-suppressive role in cancers due to deletion or loss of expression." (PMID 38046902, 2023). "Out of 151 somatic TE insertions, 148 tumor-specific insertions were associated with a total of 79 genes, while 3 genes DLC1, UBE2F, and UBE2F-SCLY were affected by the normal-specific insertions." (PMID 35013466, 2022). "Tumor formation in nude mice implicated that sh-LINC00114 reduced the tumorigenic ability of Eca109 cells while si-DLC1 had the opposite effect in nude mice." (PMID 35414117, 2022). "In this regard, the RhoGAP Deleted in Liver Cancer 1 (DLC1) has been established as a bona fide tumor suppressor, characterized by frequent copy number loss or transcriptional silencing in different tumor entities." (PMID 35322810, 2022). "Very recently, a fine detailed analysis of several tumor types in the TCGA dataset revealed that tumor-associated point mutations in DLC1 also occur frequently and can impair the biological functions of its encoded protein by several mechanisms." (PMID 34727930, 2021). "Previous studies have demonstrated that DLC-1 functioned as a tumor suppressor gene and downregulation or even loss of DLC-1 expression often occurred in HCC." (PMID 34948447, 2021). "DLC1 encodes a Rho GTPase-activating protein that functions as a tumor suppressor and down-regulated in more than 95% of NSCLC and other cancers." (PMID 31681566, 2019). "Aberrant RhoA signaling during inactivation of Dlc1 has been shown to cause tumor growth and metastasis." (PMID 28358928, 2017). "As a tumor suppressor gene, the protein encoded by DLC1 can regulate the structure of the actin cytoskeleton and inhibit cell proliferation, migration, invasion and angiogenesis." (PMID 26095787, 2015). "The Dlc1 gene encodes a RhoGAP protein that regulates cell proliferation, migration and inhibits cell growth and invasion when restored in Dlc1 deficient tumor cell lines." (PMID 26353792, 2015). "The FL variant of HCC exhibited a strong DLC1 immunoreactivity that was localized in the bundles of the connective tissue surrounding the tumor cells." (PMID 25013499, 2014). "Particularly, the expression increases with the dose of the common allele, consistent with the tumor suppressive role of DLC1." (PMID 25425654, 2014). "DLC1, which encodes a GTPase-activating protein, is considered to be a tumor suppressor gene in several types of tumors (e.g., primary hepatocellular carcinoma, breast cancer, prostate cancer, non-small cell lung carcinoma and meningioma tumors)." (PMID 24587289, 2014). "A protein fragment of ∼95 kDa contained peptides corresponding to variant 4 of p120 Rho GTPase-activating protein/deleted in liver cancer-1 (p120RhoGAP/DLC1), a tumor suppressor associated with focal adhesions and caveolae/lipid rafts." (PMID 23592983, 2013). "One of the most intriguing aspects of our study is that the depletion of MKL1/2 in DLC1-deficient HCC cells and HCC mouse tumour xenografts leads to cellular senescence and thereby mimics the effect of DLC1 re-expression." (PMID 23853104, 2013).
tumor (continued). "Deletion of Dlc1 locus has been reported to be responsible for loss of protein expression in different human tumours." (PMID 22792269, 2012). "The Deleted in liver cancer 1 (Dlc1) tumour suppressor gene encodes a Rho GTPase activating protein (RhoGAP) that increases the intrinsic hydrolysis of GTP bound Rho to the inactive GDP bound form of Rho." (PMID 22792269, 2012). "The Dlc1 genetrap alone is unable to induce tumours however, in presence of K-Ras2G12D mutation, it increases tumour and metastasis frequencies compared with K-Ras2G12D mutation only mice, indicating an additive effect." (PMID 22792269, 2012). "The tumor suppressor function has been confirmed by demonstrating that loss of DLC1 expression resulted in hepatocellular carcinoma formation in a knockdown mouse model." (PMID 19912643, 2009). "Since loss of the tumor suppressor DLC1 leads to increased HCC growth, we next investigated whether the newly identified target genes VCAN, TSPAN5 and CDH2 affect tumor characteristics such as proliferation or invasion." (PMID 34771537, 2021). "Here we firstly found that DLC1 protein level decreased with age from fish at 9- to 12-month-old, and age-dependent increase of spontaneous neoplasms might also caused by down-regulation of the tumor suppressor gene." (PMID 28903430, 2017). "Therefore, in the present study we have characterized the cell morphological and cytoskeletal changes associated with each isoform transfected into a Dlc1 deficient tumour cell line." (PMID 26977077, 2016). "DLC1 encodes GTPase-activating protein with a well-documented tumor suppressor activity." (PMID 27614886, 2016). "Chromosome region 8p22 contains several tumor suppressor genes that may cooperate with Dlc1 loss to increase tumor aggressiveness." (PMID 26353792, 2015). "The results indicate that although the loss of DLC1 is a common step during hepatocarcinogenesis, this protein may be present in the tumor microenvironment." (PMID 25013499, 2014). "Furthermore, we demonstrate that MKL1/2 knockdown can be used as a therapeutic approach in DLC1-deficient HCC tumour xenografts." (PMID 23853104, 2013). "Given the unusually high number of TSGs on the short arm of chromosome 8, the inhibitory effect of DLC1 on tumor cell growth may compensate for loss of function of other TSGs." (PMID 22580498, 2012). "This might be part of the mechanisms underlying the relationship between DLC1 and tumor prognosis." (PMID 35223504, 2022). "In addition, the association of tumor-free survival rates with the DLC1 SNPs was assessed." (PMID 26095787, 2015). "To validate the expression of DLC1 in the tumor versus liver tissue, we analyzed the expression of DLC1 by immunohistochemistry." (PMID 41317652, 2026). "Collectively, these findings highlight that beyond its functional role in catalyzing RhoGTP hydrolysis, the RhoGAP domain serves as a central binding site for protein interactions that modulate DLC1’s tumor suppressor activity." (PMID 41317652, 2026). "Our findings reveal a functional equilibrium between the tumor-suppressive DLC1-FLNA and oncogenic MRTF-A-FLNA complexes, controlled by FLNA phosphorylation at serine 2152 (FLNA pSer2152)." (PMID 41317652, 2026). "DLC1’s tumor-suppressive effects are known to depend on its localization at focal adhesions and interaction with proteins such as talin and focal adhesion kinase (FAK)." (PMID 41317652, 2026). "In liver tumorigenesis, the induction of senescence acts as a tumor-suppressive mechanism, making DLC1 rescue amenable to HCC therapies." (PMID 41317652, 2026). "Nevertheless, the TNS4–DLC1 interaction is crucial for DLC1’s tumor-suppressive activity by enabling its localization to focal adhesions." (PMID 40906372, 2025). "In this context, the GAP protein Deleted in Liver Cancer 1 (DLC1), with specificity mainly for RhoA and, to a lesser extent Cdc42, has been established as an important tumor suppressor." (PMID 40354489, 2025).
tumor (continued). "In tumour cells, the oncogene DLC1 tends to be inactivated, a process that not only upregulates the expression of FAK and talin, but also inhibits RhoA signalling, which in turn attenuates the contractility of the actin cytoskeleton." (PMID 40045379, 2025). "Our work highlights the central role of DLC1 in cellular plasticity, underscoring its significance as a tumor suppressor." (PMID 40354489, 2025). "Conversely, preventing nuclear protein export contributes to the antitumor activity of KRAS inhibition, which can be further augmented by reactivating the tumor suppressor activity of DLC1 or potentially combining RAS inhibitors with other cancer treatments." (PMID 39528835, 2024). "On the other hand, CAF2 lowered the expression of the tumor- and metastasis-suppressor DLC1, as well as CDH1 in estrogen-unstimulated conditions, further indicative of induction of EMT." (PMID 38388711, 2024). "Mouse-specific cells (vCM_mouse) also expressed higher levels of Pcdh7, calcium-dependent adhesion molecule, as well as Dlc1, a Rho GTPase activating protein with tumor suppressor function that is essential for embryonic development." (PMID 36401619, 2023). "The low expression of DLC1 signifies an advanced tumor-node-metastasis stage, node metastasis, increased tumor size, increased lymph deeper tumor invasion, and an elevated distant metastasis rate." (PMID 36984515, 2023). "Many tumor suppressors such as Deleted in Liver Cancer 1(DLC1) and Large tumor suppressor, homolog 2 (LATS2), downregulated in colon cancer cells, are upregulated followed by ERβ expression and targeted by miRNAs." (PMID 36207986, 2023). "The restoration of DLC1 expression in cancer cells induced apoptosis and senescence; inhibited cell growth, migration, and invasiveness; and reduced tumor formation." (PMID 35223504, 2022). "Collectively, interfering with LINC00114 elevated DLC1 expression to inhibit EC tumor growth in vivo." (PMID 35414117, 2022). "The DLC1 gene (deleted in liver cancer 1, STARD12, ARHGAP7) encodes a ubiquitously expressed Rho GTPase-activating protein that is a tumor suppressor and can regulate RhoA activity both in vitro and in vivo." (PMID 35970859, 2022). "We first analyzed the expression of DLC1 in multiple tumor and normal tissue types using the TCGA database to explore DLC1 expression in cancer and normal tissues." (PMID 35223504, 2022). "Genomic alterations in DLC1 contribute to drug sensitivity and confer growth advantage upon activation of RHO-ROCK signalling, rendering tumour cells more susceptible to ROCK-inhibitors (e.g., Y-27632)." (PMID 35963849, 2022). "On the molecular level, the tumor suppressive function of DLC1 has been mainly ascribed to its RhoGAP activity." (PMID 35322810, 2022). "For example, DNA methylation interferes with the expression of the deleted in the liver cancer 1 (DLC-1) gene, leading to the initiation of HCC as the gene encodes a tumor suppressor." (PMID 35082931, 2022). "The role of TNS2 in tumorigenesis is quite unclear, as it has been reported to promote cell migration and proliferation but also to contribute to the tumor-suppressive function via binding to the PTB domain of deleted in liver cancer 1 (DLC1) protein." (PMID 35804982, 2022). "Our study first analyzed the expression of DLC1 in multiple tumor and normal tissue types using the TCGA database, displaying that DLC1 expression significantly declined in UCEC." (PMID 35223504, 2022). "We found DLC1 with lower expression levels in tumor samples; patients with the high expression of DLC1 exhibited prolonged survival." (PMID 35223504, 2022). "In the high-DLC1 expression group, tumor immunity-related signaling pathways, such as Wnt signaling pathway, leukocyte transendothelial migration, and JAK–STAT signaling pathway, were markedly enriched." (PMID 35223504, 2022).
tumor (continued). "Within this region, there are established tumor suppressors (DLC1, DOK2 and LZTS1), as well as potential tumor suppressor genes (CSMD1, MTUS1, and MSR1), and many other genes not established in cancers." (PMID 35994499, 2022). "A study showed that restoring DLC1 expression in cancer cells induced apoptosis and senescence, inhibited migration and invasiveness, and reduced tumor formation." (PMID 35223504, 2022). "In this study, the Wilcoxon rank-sum test displayed that the DLC1 expression significantly decreased in the tumor samples compared with normal ones." (PMID 35223504, 2022). "In contrast, several factors assigned to the suppression of tumor cell migration and/or invasion as well as angiogenesis, such as DLC1, RHOU, DACH1, and RECK, were significantly downregulated in the brain-seeking cell line in comparison with the native one." (PMID 35163822, 2022). "Quantitative analyses of graded scores displayed prominent DLC1 staining in intestinal-type, differentiated tumours both in the cytoplasm and at membranes, compared with diffusetype, undifferentiated tumours with marked stroma positivity." (PMID 35963849, 2022). "In this study, we assessed the expression of DLC1 in 33 different types of cancers using the TCGA database, so as to reveal the differences between tumor and normal tissue expression of DLC1 in many cancers." (PMID 35223504, 2022). "The same effect was also observed when Caveolin-1 was overexpressed, confirming, as previously reported, that Caveolin-1 contributes to the tumor suppressor activity of DLC1." (PMID 34727930, 2021). "DLC1, a tumor suppressor gene that is downregulated in many cancer types by genetic and nongenetic mechanisms, encodes a protein whose RhoGAP and scaffolding activities contribute to its tumor suppressor functions." (PMID 34727930, 2021). "Our previous studies in LUAD lines that express readily detectable levels of DLC1 protein indicated AKT and SRC kinases directly phosphorylate and attenuate the Rho-GAP and tumor suppressor activities of DLC1." (PMID 34862367, 2021). "In this way, we found that a number of well-known oncogenes, including MYC and SOX9, were annotated as targets of tumor-specific SEs, while several tumor suppressor genes in LUAD, such as DLC1 and RB1, were linked to normal-specific SEs." (PMID 34001209, 2021). "Together, these findings lead to the conclusion that DLC1 exerts some of its tumor suppresive effects via GAP-independent mechanisms." (PMID 34727930, 2021). "The importance of these activities for tumorigenesis is supported by our analysis of 7 cancer-associated DLC1-START mutants, each of which has reduced tumor suppressor function but retains wildtype RhoGAP activity." (PMID 34727930, 2021). "These rational drug combinations induce potent tumor growth inhibition, with markers of apoptosis and senescence, that is highly dependent on DLC1 protein." (PMID 34862367, 2021). "Cdk5 phosphorylates and activates the tumor suppressor DLC1, thus reducing the size of xenografted tumor in mice." (PMID 34814918, 2021). "Especially, some tumor suppressor genes (TSGs) including DLC1 and SYNE1, which have been found to be downregulated in our GII tumor samples compared to GI samples, were predominantly mutated in GII-like TCGA patients." (PMID 34001209, 2021). "The authors subsequently proved that miR-483-3p overexpression increased cell proliferation targeting directly DLC-1 which is a tumor suppressor involved in many types of cancer." (PMID 34484116, 2021). "We further discovered the possible role of tumor suppressors DLC1 and HLF in AURKB-mediated adverse outcome of LUAD." (PMID 33612479, 2021). "To explore the expression of EZH2 and DLC1 in tumours, we analysed the expression of EZH2 and DLC1 in various tumours based on the secondary online tools of the TCGA database." (PMID 32725802, 2020).
tumor (continued). "The knockdown of DLC-1 increases GTP-bound RhoA and tumorigenic growth, and expression of constitutively active RhoA in these cells accelerate liver tumor formation, suggesting that DLC-1 acts as tumor suppressor." (PMID 32392742, 2020). "Taken together, our data identify several conserved residues likely to underlie the START-directed regulation of DLC-1 and DLC-2 tumor-suppressive capabilities." (PMID 33142932, 2020). "The DLC-1 protein represents a well characterized tumor suppressor subjective to proteasome-mediated degradation." (PMID 33148199, 2020). "If DLC-1 can inhibit the immunosuppression of hMSCs, it then exerts its tumor suppressor functions on both seeds (tumor cells) and soil (mesenchymal cells) in tumor microenvironment according to the ‘seed-soil’ theory of tumorigenicity." (PMID 33148199, 2020). "Deleted in liver cancer 1 (DLC1, also known as ARHGAP7) is typically thought of as a tumor suppressor, however, studying the miR-200 family discovered the inconsistent effects of targeting on cancer progression." (PMID 32353968, 2020). "IHC showed that the expression of EZH2 was down‐regulated and the expression of DLC1 was up‐regulated in TNBC xenograft tumour tissues treated with curcumin." (PMID 32725802, 2020). "The Deleted in Liver Cancer-1 (DLC-1) protein has been established as a tumor suppressor with abilities to inhibit growth, migration, invasion and metastasis of a large variety of common cancers." (PMID 33148199, 2020). "In comparison, genomic deletion and/or aberrant methylation occurring frequently for DLC-1 in different human cancers represent the more rigid mechanism(s) necessary for tumor cells to achieve a complete knock-down of the tumor suppressor functions of DLC-1." (PMID 33148199, 2020). "The present study uncovers a novel function of DLC-1 tumor suppressor in regulating the immunomodulation of hMSCs." (PMID 33148199, 2020). "DLC1 encodes for an RHO GTPase accelerating protein (GAP) that plays a role in the regulation of GTP binding proteins and functions as a potent tumor suppressor gene in several cancers including breast cancer." (PMID 32051475, 2020). "Loss of DLC1-3 expression is observed in many human cancers, and the restoration of DLC1 expression leads to the inhibition of tumour growth in vitro, indicating that the DLC proteins are tumour suppressor proteins." (PMID 29545526, 2018). "Deleted in Liver Cancer-1 (DLC1), a member of the RhoGAP family of proteins, functions as a tumor suppressor in several cancers including breast cancer." (PMID 30278072, 2018). "DLC1 has been well characterized as a tumor suppressor protein, suppressing tumor growth and metastasis through its RhoGAP domain to inhibit RHO signaling activity." (PMID 29084958, 2017). "After long-term feeding, resveratrol inhibited age-associated liver spontaneous neoplasms and increased expression of SIRT1 and DLC1 and their interaction." (PMID 28903430, 2017). "Overexpression of SIRT1 decreased AKT (PKB) level and further inhibited phosphorylation of DLC1 in spontaneous neoplasms by resveratrol." (PMID 28903430, 2017). "In spontaneous neoplasms, we found that resveratrol decreased phosphorylation of DLC1 and up-regulated its tumor suppressor activity in vivo." (PMID 28903430, 2017). "So we detected downstream proteins of DLC1 and FoxOs to explore mechanism that resveratrol induced apoptosis in spontaneous neoplasms." (PMID 28903430, 2017). "It is demonstrated that tumor suppressor functions of DLC1 depend on its RhoGAP activity, as well as on some GAP-independent mechanisms." (PMID 27588930, 2017). "Our previous results show that the full tumor suppressor activity of DLC1 depends on its LD-like motif, which binds talin and FAK, and cooperation between tensin binding and RhoGAP activity." (PMID 28903430, 2017). "DLC1 was the first family member identified, and a considerable amount of clinical and experimental evidence has established it as a bona fide tumor suppressor gene." (PMID 27174913, 2016).